DIRAS2 (DIRAS family GTPase 2)
Description:
Displays low GTPase activity and exists predominantly in the GTP-bound form.
Synonyms: Di-Ras2; DKFZp761C07121
Tractability: Small molecule: a structure with a bound ligand is known. Antibody: UniProt places it where antibodies can reach, with high confidence; its Gene Ontology location is reachable by antibodies, with high confidence. PROTAC: UniProt records ubiquitination sites on it; ubiquitination databases record sites on it; its protein half-life has been measured.
Gene: Protein-coding gene on chromosome 9 (90,609,832 to 90,642,862, reverse strand). Ensembl gene ENSG00000165023.
Subcellular location: Cell membrane
Gene Ontology:
Molecular function: GTP binding; GTPase activity; protein binding
Biological process: positive regulation of MAP kinase activity; small GTPase-mediated signal transduction; signal transduction
Cellular component: plasma membrane; membrane
Genetic constraint (gnomAD): Loss-of-function variants: 5 observed, 13.44 expected, observed/expected ratio (o/e) 0.37, 90% interval 0.19 to 0.78. The upper end of that interval is the gene's LOEUF score, 0.78, which puts it in group 3 of 6, group 1 being the genes least tolerant of losing a copy. Missense variants: 191 observed, 278.82 expected, observed/expected ratio (o/e) 0.69, 90% interval 0.61 to 0.77. Synonymous variants: 111 observed, 112.39 expected, observed/expected ratio (o/e) 0.99, 90% interval 0.85 to 1.16.
Homologues: Orthologues: chimpanzee DIRAS2 (100% identical), macaque DIRAS2 (100% identical), mouse Diras2 (99% identical), rat Diras2 (99% identical), guinea pig DIRAS2 (98% identical), pig DIRAS2 (98% identical), dog DIRAS2 (97% identical), rabbit DIRAS2 (97% identical), tropical clawed frog diras2 (93% identical), Drosophila melanogaster CG8500 (76% identical). Paralogues in human: DIRAS1 (79% identical), DIRAS3 (48% identical), RAP2A (41% identical), RASD2 (41% identical), RAP2B (40% identical), RAP2C (40% identical), RAP1A (39% identical), RAP1B (39% identical), RASD1 (39% identical), KRAS (36% identical), RRAS2 (36% identical), RRAS (35% identical), and 23 more.
Diseases named in the same sentence as DIRAS2 in open-access papers:
DIRAS2 is named in the same sentence as 21 diseases in open-access papers, as found by Europe PMC text mining. Sharing a sentence is not in itself a finding about the gene and the disease. The quoted sentences say what the papers report.
colorectal cancer (3 papers, 2022 to 2023). A primary or metastatic malignant neoplasm that affects the colon or rectum. "It has also been found that the DIRAS2 gene reduces the overall survival of colorectal cancer patients by blocking the enhancer signaling pathway that activates nuclear factor B." (PMID 37670166, 2023). "PSMD2 also reduces the protein levels of a variety of Ras-related GTPase, including DIRAS family GTPase 2 (DIRAS2) through the proteasome-mediated pathway and subsequently blocks the NF-κB signalling pathway and suppresses cell proliferation in colorectal cancer." (PMID 37875476, 2023).
ovarian carcinoma (3 papers, 2021 to 2022). A malignant neoplasm originating from the surface ovarian epithelium. "It has been reported that DIRAS2 was downregulated in ovarian cancer and was associated with decreased overall and disease-free survival, which was consistent with the findings of our study." (PMID 36106120, 2022). "Sutton and colleagues showed that expression of DIRAS-1 and DIRAS-2 is downregulated in ovarian cancer and associated with decreased disease-free and overall survival." (PMID 34680261, 2021). "Experiments in vitro confirmed that overexpression of DIRAS1 and DIRAS2 reduced the growth of ovarian cancer cells." (PMID 35651810, 2022).
renal cell carcinoma (3 papers, 2021 to 2025). "DIRAS2 has been demonstrated to promote renal cell carcinoma formation by activating the mitogen-activated protein kinase pathway." (PMID 40569389, 2025). "Another study in renal cell carcinoma, however, indicates a potential oncogenic function of DIRAS-2 because overexpression of DIRAS-2 in clear cell renal cell carcinoma cells led to increased cell proliferation, migration, and invasion in the absence of von Hippel–Lindau protein." (PMID 34680261, 2021).
clear cell renal cell carcinoma (2 papers, 2021 to 2022). "In clear cell renal cell carcinoma (ccRCC), however, DIRAS-2 exhibited a potential oncogenic function, which is in contrast to all other published studies." (PMID 34680261, 2021). "displayed that DIRAS2 could potentially function as an oncogene in clear cell renal cell carcinoma." (PMID 35651810, 2022).
pancreatic cancer (2 papers, 2024 to 2025). "The full rescue of MAPK activation upon USP10 knockdown by DIRAS2 ectopic expression shown in this study indicates that the effect of USP10 on the MAPK signal is mediated by DIRAS2 in pancreatic cancer cells." (PMID 39314885, 2024). "We further confirmed that endogenous DIRAS2 bound to endogenous USP10 in PANC1 pancreatic cancer cells, indicating that the binding is physiologically relevant (bottom)." (PMID 39314885, 2024). "Our most recent study showed that UBE2F knockdown inhibited growth and survival of pancreatic cancer cells in vitro, and suppressed pancreatic tumorigenesis induced by KrasG12D in vivo via inducing accumulation of DIRAS2, a RAS inhibitor to block the MAPK/c-Myc signals." (PMID 39762645, 2025). "Biologically, given that DIRAS2 plays a tumor suppressor role in pancreatic ductal adenocarcinoma (PDAC) induced by KrasG12D4, we hypothesized that USP10 would likely regulate the growth of pancreatic cancer cells via stabilizing DIRAS2." (PMID 39314885, 2024). "Likewise, in both PANC1 and Miapaca‐2 pancreatic cancer cells, USP10 overexpression increased DIRAS2 levels and inactivated pERK1/2 in a dose‐dependent manner (top left), whereas USP10 knockdown decreased DIRAS2 levels and activated pERK1/2 (top right)." (PMID 39314885, 2024).
attention deficit-hyperactivity disorder (1 paper, 2014). A disorder characterized by a marked pattern of inattention and/or hyperactivity-impulsivity that is inconsistent with developmental level and clearly interferes with functioning in at least two settings (e.g. at home and at school). "DIRAS1 is likely to be a neural tumor suppressor, and DIRAS2 is associated with an adult form of attention deficit hyperactivity disorder." (PMID 24523945, 2014).
brain tumors (1 paper, 2021). "We investigated the genes DIRAS-1 and DIRAS-2 in terms of their regulation and functional relevance in brain tumors (gliomas)." (PMID 34680261, 2021).
cutaneous melanoma (1 paper, 2025). A primary melanoma arising from atypical melanocytes in the skin. "Furthermore, DIRAS2 has been identified as a tumor suppressor gene in cutaneous melanoma by inhibiting the Wnt/β-catenin signaling pathway and is associated with immune infiltration." (PMID 40083697, 2025).
glioma (1 paper, 2021). A benign or malignant brain and spinal cord tumor that arises from glial cells (astrocytes, oligodendrocytes, ependymal cells). "All these findings provide evidence for downregulation of DIRAS-1- and DIRAS-2 as a mechanism of chemoresistance in gliomas." (PMID 34680261, 2021).
melanoma (1 paper, 2022). A malignant, usually aggressive tumor composed of atypical, neoplastic melanocytes. "Furthermore, DIRAS2 depletion promoted melanoma growth and metastasis in vivo." (PMID 35651810, 2022).
Parkinson disease (1 paper, 2019). A progressive degenerative disorder of the central nervous system characterized by loss of dopamine producing neurons in the substantia nigra and the presence of Lewy bodies in the substantia nigra and locus coeruleus. "The results also showed a number of genes that decreased in an Mn dose-dependent manner which include genes involved in iron transport (TF), protective activity of telomeres (TERF2), neurosensory function (MYO15a, OR1F1), and neurological disease such as ADHD (DIRAS2) and Parkinson’s disease (FRK)." (PMID 31396262, 2019).
personality disorder (1 paper, 2022). A diverse category of psychiatric disorders characterized by behavior that deviates markedly from the expectations of the individual's culture; this pattern of deviation is pervasive and inflexible and is stable over time. "The GTP-binding RAS-like 2 gene (DIRAS2), which regulates neurogenesis, as well as protein phosphatase 2, regulatory subunit B, gamma (PPP2R2C) gene located in the 4P16 region, channel-interacting protein 4 (KCNIP4) and SPOCK gene, is also associated with adult ADHD and personality disorders." (PMID 36317794, 2022).
thyroid tumorous (1 paper, 2022). "SLC25A15, DIRAS2, PLA2R1, and MTARC1 expression was downregulated in thyroid tumorous tissues with LNM compared thyroid tumorous tissues with NLNM, which was validated using the TCGA dataset." (PMID 36106120, 2022).
tumor (8 papers, 2014 to 2025). "HP significantly reduced DIRAS2 abundance in tumor tissue and exerted an inhibitory effect on tumor cell proliferation." (PMID 41101498, 2025). "HP significantly reduced the abundance of DIRAS2 in the tumor tissue, thereby inhibiting tumor cell proliferation, whereas HS promoted proliferation by increasing DIRAS2 expression." (PMID 41101498, 2025). "DIRAS2 functions as a tumor suppressor gene in cases of SKCM by inhibiting the Wnt/β-catenin signaling." (PMID 35651810, 2022). "It was found here that DIRAS2 expression is significantly different in SKCM tumor tissues and paracancerous normal tissues, and is low in SKCM tumor tissues, using the GEPIA online database; the same result was obtained in GEO data set verification." (PMID 35651810, 2022). "Our study confirmed the tumor-suppressing properties of DIRAS2; it is indeed a tumor suppressor gene in SKCM." (PMID 35651810, 2022). "Our findings thus indicate that DIRAS2 serves as a tumor-suppressor gene, with the potential to be a prognostic and therapeutic target in CRC." (PMID 35173535, 2022). "In vitro experiments suggested that proliferation, migration, invasion, and metastasis of SKCM tumor cells were distinctly enhanced after DIRAS2 knockdown." (PMID 35651810, 2022). "Based on the findings, including the results of in vitro tests, it was observed that DIRAS2 is a tumor suppressor gene for SKCM, with the Wnt/β-Catenin signaling pathway being the negatively regulated target." (PMID 35651810, 2022). "The findings revealed that the DIRAS2 down-regulated group’s alveolar tissues included denser tumor cell islands than the control group." (PMID 35651810, 2022). "This may imply that DIRAS2 regulates tumor-related cytokine expression by affecting the Wnt/β-catenin signaling pathway." (PMID 40083697, 2025). "The top 100 genes in the GEPIA database were selected, that have the highest relevance to DIRAS2 expression in SKCM to explore the pathways that DIRAS2 may be involved in modulating tumor progression in SKCM." (PMID 35651810, 2022). "Moreover, western blot results of 71.4% (15/21) of CRC tissue samples demonstrated reduced DIRAS2 protein expression in the tumor." (PMID 35173535, 2022). "The proliferation of tumor cells was notably enhanced after knocking down DIRAS2." (PMID 35651810, 2022). "We also noted that the tumor-suppressing activity of DIRAS2 could be overridden by PSMD2." (PMID 35173535, 2022). "Although numerous studies have confirmed the tumor-suppressor effect of the DIRAS family, DIRAS2 can also act as a tumor activator." (PMID 35173535, 2022). "Comparative analyses of these DEPs revealed downregulated expression of specific proteins with well-established links to tumor metastasis, such as SLC25A15, DIRAS2, PLA2R1, and MTARC1." (PMID 36106120, 2022). "In our investigation, we proved that DIRAS2 inhibited cellular proliferation in CRC and induced G0/G1 arrest, affirming its tumor-suppressor function." (PMID 35173535, 2022). "To further confirm whether PSMD2 is critical to DIRAS2-mediated tumor-suppression activity, we performed a PSMD2 rescue experiment, and our functional study revealed that PSMD2 OV reversed DIRAS2-inhibited cellular proliferation." (PMID 35173535, 2022). "In other words, DIRAS2 has a significant effect on SKCM immune infiltration, while the positive effect of DIRAS2 on SKCM may be related to the high density of these TICs, and DIRAS2 may play an important role in the regulation of the tumor immune microenvironment in SKCM patients." (PMID 35651810, 2022). "Finally, in order to detect whether DIRAS2 affected SKCM growth, proliferation, and/or migration, we carried out a series of cytological experiments that involved down-regulation of DIRAS2 and deeply studied tumor cell functions." (PMID 35651810, 2022). "However, the role of DIRAS2 in SKCM has not been investigated (i.e., whether it is a tumor suppressor gene or an oncogene)." (PMID 35651810, 2022).
cancer (5 papers, 2021 to 2025). A tumor composed of atypical neoplastic, often pleomorphic cells that invade other tissues. "In summary, our study highlights the epigenetic impact of STAT3 acetylation on DIRAS2 expression and reveals a potential feedback loop involving TAMs and cancer cells." (PMID 40083697, 2025). "Downregulation of DIRAS2 plays a pivotal role in cancer progression and predicts poor prognosis in tumors." (PMID 36106120, 2022). "In vitro experiments were conducted to confirm that DIRAS2 indeed has anti-cancer functions in SKCM cells." (PMID 35651810, 2022). "The contradictory roles of DIRAS2 in various cancers may thus result from tissue-specific and cancer-specific paradigms." (PMID 35173535, 2022).
infection (1 paper, 2022). The state of being infected such as from the introduction of a foreign agent such as serum, vaccine, antigenic substance or organism. "Second, we used real-time quantitative reverse transcription-PCR (qRT-PCR) to measure the expression levels of several candidate RIDD genes, including Bloc1s1, Cd300lf, Diras2, and Txnip during infection." (PMID 35587649, 2022).
DIRAS2 also shares sentences with these, for which no sentence is quoted: breast carcinoma (1 paper); breast tumors (1); neurological disease (1); osteoporosis (1); pancreatic ductal adenocarcinoma (1).